CCDC87 (coiled-coil domain containing 87)
Description:
Plays a role in spermatogenesis, where it is important for normal sperm head morphology. Also required for the acrosome reaction and thus normal male fertility.
Synonyms: FLJ10786
Tractability: PROTAC: ubiquitination databases record sites on it.
Gene: Protein-coding gene on chromosome 11 (66,590,176 to 66,593,063, reverse strand). Ensembl gene ENSG00000182791.
Subcellular location (Human Protein Atlas): Cytosol; Nucleoli; Nucleoplasm
Gene Ontology:
Molecular function: protein binding
Biological process: positive regulation of acrosome reaction; positive regulation of fertilization
Genetic constraint (gnomAD): Missense variants: 1,060 observed, 1,075.2 expected, observed/expected ratio (o/e) 0.99, 90% interval 0.94 to 1.04. Synonymous variants: 430 observed, 448.28 expected, observed/expected ratio (o/e) 0.96, 90% interval 0.89 to 1.04.
Homologues: Orthologues: chimpanzee CCDC87 (99% identical), macaque CCDC87 (94% identical), dog CCDC87 (70% identical), rabbit CCDC87 (68% identical), pig CCDC87 (67% identical), guinea pig CCDC87 (62% identical), mouse Ccdc87 (61% identical), rat Ccdc87 (60% identical), tropical clawed frog ccdc87 (27% identical), zebrafish ccdc87 (6% identical).
Diseases named in the same sentence as CCDC87 in open-access papers:
CCDC87 is named in the same sentence as 2 diseases in open-access papers, as found by Europe PMC text mining. Sharing a sentence is not in itself a finding about the gene and the disease. The quoted sentences say what the papers report.
male infertility (1 paper, 2023). The inability of the male to effect fertilization of an ovum after a specified period of unprotected intercourse. "Knockout of Ccdc9, Ccdc38, Ccdc42, Ccdc62, Ccdc87 and Ccdc136 results in male infertility in mouse models because of defects in sperm flagella." (PMID 37601242, 2023).
vitiligo (1 paper, 2025). Generalized well circumscribed patches of leukoderma that are generally distributed over symmetric body locations and is due to autoimmune destruction of melanocytes. "Finally, we obtained ten matched genes (GP1BA, ANKS4B, CCDC87, CA8, HLA‐DOB, RHEBL1, NLRP7, GZMH, HERPUD1, and MAP2K1) as a vitiligo‐gene signature (VGS)." (PMID 40974370, 2025).